SPX (spexin hormone)
Diseases named in the same sentence as SPX in open-access papers (continued):
Sharing a sentence is not in itself a finding about the gene and the disease.
Anorexia (1 paper, 2022). Lack of desire to eat (loss of appetite). "Our results revealed that SPX induces anorexia and leptin increases SPX expression via STAT3 signaling in the mouse hypothalamus, suggesting a possible role for SPX in the mediation of leptin’s anorexigenic effects in the hypothalamus." (PMID 35204737, 2022). "In this study, we report that GALR2 is involved in SPX’s effects on leptin-induced anorexia and POMC expression." (PMID 35204737, 2022). "In this study, we found that central SPX induces anorexia and increases hypothalamic POMC mRNA expression." (PMID 35204737, 2022). "Together, these findings indicate that GALR2 is involved in SPX’s effects on leptin-induced anorexia." (PMID 35204737, 2022). "Thus, we sought to identify whether SPX action on leptin-induced anorexia is mediated via GALR2 and/or GALR3." (PMID 35204737, 2022).
behavioral disorders (1 paper, 2021). "In recent years, SPX has been implicated in mood/behavioral disorders and other metabolic diseases, and emerged as a new target for drug development, e.g., for SPX-based GalR2 analogs with anxiolytic/antidepressive activity but reduced propensity for receptor desensitization." (PMID 34025589, 2021).
eating disorder (1 paper, 2022). A broad group of psychological disorders with abnormal eating behaviors leading to physiological effects from overeating or insufficient food intake. "Longitudinal studies simultaneously measuring leptin and SPX in eating disorders and adjusting for BMI and body fat mass are needed, to further investigate the relationship between SPX and leptin and the function of SPX in eating disorders." (PMID 36079049, 2022). "Therefore, one might conclude that SPX is not involved in the pathogenesis of AN in terms of impaired eating habits as an expression of eating disorder psychopathology." (PMID 36079049, 2022).
kidney damage (1 paper, 2024). "Further investigations are warranted to gain a comprehensive understanding of kidney damage, and specifically to elucidate the role of SPX in this context." (PMID 38234666, 2024). "A study reported that intra-cerebroventricular administration of SPX exhibited a protective effect on kidney damage." (PMID 38234666, 2024). "Additionally, these studies can pave the way for exploring novel therapeutic strategies targeting SPX to prevent and/or treat the development of kidney damage." (PMID 38234666, 2024). "The ADR group (c) showed a statistically significant increase in SPX immunoreactivity when compared to the control group (P=0.004), indicating up-regulation of SPX in response to ADR-induced kidney damage." (PMID 38234666, 2024).
kidney injury (1 paper, 2024). Trauma to the kidney. "Based on the observed changes in SPX levels in the injured and treatment groups, it can be inferred that SPX may contribute to the pathogenesis of ADR-induced kidney injury." (PMID 38234666, 2024).
nematode infection (1 paper, 2020). "When compared with sequences in databases, similarities were found with other nematode proteins, for example As16 from Ascaris suum, Ag2 from Baylisascaris schroederi, As14 from A. suum, and nematode infection markers such as SPX antigens from Brugia malayi and Wuchereria bancrofti." (PMID 33371317, 2020).
prediabetes (1 paper, 2019). "In conclusion, increased circulating SPX levels among adults with prediabetes are observed following favorable glycemic changes post-lifestyle modification program, particularly in females." (PMID 31263247, 2019).
metabolic disease (6 papers, 2021 to 2026). A congenital disorder (due to inherited enzyme abnormality) or acquired (due to failure of a metabolically important organ) disorder resulting from an abnormal metabolic process. "A dysregulation in SPX signaling can potentially affect food consumption behavior and adipose tissue regulation, leading to metabolic disorders." (PMID 35692389, 2022). "Thus, it can be presumed that peripheral SPX is dysregulated in metabolic disorders, allowing for an increase in food consumption and body weight." (PMID 35692389, 2022).
cardiovascular disease (4 papers, 2021 to 2026). "This review concisely summarizes the distribution and regulation of SPX, with a focus on its emerging roles in the pathogenesis of cardiovascular disease and its potential as a theranostic agent." (PMID 41788558, 2026).
psychiatric disorder (4 papers, 2021 to 2023). A disorder characterized by behavioral and/or psychological abnormalities, often accompanied by physical symptoms. "Nevertheless, increased knowledge of the potential involvement of SPX, PNX, kisspeptin and nesfatin-1 in psychiatric disorders such as BD may help in the future development of therapeutic interventions targeting the signaling pathways of specific neuropeptides." (PMID 38255190, 2023).
cancer (1 paper, 2025). A tumor composed of atypical neoplastic, often pleomorphic cells that invade other tissues. "Through GWAS, eQTL, and transcriptomic analyses, we identified key genes, such as SPX, and their complex regulatory patterns across these three cancers." (PMID 41231350, 2025). "In EC, although relevant research is scarce, literature has indicated that SPX may participate in metabolic regulation in cancer cells." (PMID 41231350, 2025). "We found complex regulatory patterns of key genes, such as SPX, in these three cancers, and that metabolic reprogramming, neuro-regulation, and epigenetic modifications may constitute their shared pathological foundation." (PMID 41231350, 2025).
infection (1 paper, 2022). The state of being infected such as from the introduction of a foreign agent such as serum, vaccine, antigenic substance or organism. "To evaluate protection from infection, we challenged T cells and macrophages from WT and CCR5mut-fib-iPSCs with the T cell-tropic SIVmac239 and macrophage-tropic SIVmac316 open SpX virus isolates." (PMID 35364011, 2022).
tumor (1 paper, 2025). "Notably, the SPX gene exhibited a negative correlation with OC and CC in SMR analysis, but its expression direction in tumor tissues showed disease-specific differences." (PMID 41231350, 2025).
SPX also shares sentences with these, for which no sentence is quoted: metabolic dysfunction-associated steatotic liver disease (3 papers); preeclampsia (3); chronic kidney disease (2); atherosclerosis (1); cataract (1); cervical cancer (1); diabetic retinopathy (1); fibrosis (1); general anxiety disorder (1); inflammation (1); kidney diseases (1); myocardial infarction (1); pancreatic cancer (1); rheumatoid arthritis (1); virus infection (1).